TFF1 (trefoil factor 1)
Diseases named in the same sentence as TFF1 in open-access papers (continued):
Sharing a sentence is not in itself a finding about the gene and the disease.
gastric tumor (20 papers, 2009 to 2025). "Transient IFNγ exposure caused stable repression of TFF1, a gastric tumor suppressor frequently lost in H. pylori-associated cancer." (PMID 41573568, 2025). "Several reports have demonstrated that TFF1 functions as a gastric tumor suppressor gene, and loss of Tff1 leads to development of dysplastic lesions and adenocarcinoma in antropyloric gastric tissues in mice." (PMID 25980439, 2015). "In this regards, more than half of human gastric tumors lack TFF1 expression because of promoter hypermethylation, mutations or deletions of the TFF1 gene." (PMID 25015107, 2014). "In human primary gastric tumors, there is a frequent loss of TFF1 expression whereas disruption of the mouse Tff1 gene leads to the development of gastric dysplasia and carcinomas in mice." (PMID 25015107, 2014). "TFF1 is among the genes frequently hypermethylated in this context, with methylation observed in over 50% of H. pylori-positive gastric tumors." (PMID 41573568, 2025). "Conditional, Tff1:CreERT transgene-mediated Yap1 gene knockout in the gastric epithelium of Gp130FF mice reduced gastric tumor incidence." (PMID 37957015, 2024). "To assess the effects of Yap1 on gastric tumor initiation, we also administered tamoxifen to Gp130FF; Tff1:CreERT2; Yap1fl/fl mice at 9 wk of age." (PMID 37957015, 2024). "The authors stated that TFF1 was found as a gastric tumor suppressor and, at the cellular level, TFF1 promotes cell differentiation while limiting cell proliferation and apoptosis." (PMID 37389790, 2024). "Trefoil factor 1 (TFF1) is involved in gastric tumor suppression; it is lost in more than 50% of GC cells because of epigenetic silencing, TFF1 deletions, or its transcription factors downregulation." (PMID 37037466, 2023). "This is a further step towards understanding the molecular function of TFF1, particularly as a gastric tumor suppressor." (PMID 32260357, 2020). "In gastric tumors a decrease of TFF1 significantly reduced the apoptosis of the cell lines and facilitated their proliferation." (PMID 27081700, 2016). "In this study, we investigated the role of TFF1 in suppressing H. pylori-induced activation of β-catenin using in vitro and in vivo gastric neoplasm models." (PMID 25980439, 2015). "TFF1 expression is strongly induced after mucosal injury and it has been proposed that tff1 functions as a gastric tumor suppressor gene." (PMID 24236136, 2013). "We investigated co-expression of TFIZ1 and TFF1 in a series of 15 primary gastric tumours and corresponding metastatic tumour cells." (PMID 18722547, 2009). "In the stomach, TFF1 promotes mucosal healing by enhancing cell migration, inhibiting apoptosis, and promoting angiogenesis, and plays an important role in healing mucosal damage, such as gastric ulceration, and in suppressing gastric tumour formation." (PMID 39596084, 2024). "Associated to mucins, too, is the family of trefoil factors, including the gastric tumor suppressors TFF1 and TTF2, which are co-localized with MUC5AC and MUC6, respectively; and TFF3, which is typically not secreted by gastric mucosa but, like MUC2, by goblet cells." (PMID 34227026, 2021). "Collectively, all these date indicate that TFF1 is a gastric tumor suppressor gene." (PMID 32260357, 2020). "The reactive CysVII of monomeric TFF1 could not only have intracellular and extracellular protective functions as a gastric tumor suppressor." (PMID 32630599, 2020). "For in vivo validation, we utilized the Tff1-KO gastric neoplasm mouse model." (PMID 25980439, 2015). "Work with TFF1-null mice showed that TFF1 is a gastric tumour suppressor." (PMID 18722547, 2009). "Therefore, it has been proposed that TFF1 functions as a gastric tumor suppressor gene." (PMID 24236136, 2013). "TFF1 protein expression is also lost in gastric tumours, but in about half the cases in which TFIZ1 protein was not expressed, TFF1 expression was detected." (PMID 18722547, 2009).
gastric tumor (continued). "The finding that TFF1 is expressed in the absence of TFIZ1 in some gastric tumours and further that an ability to express TFF1 but not TFIZ1 is acquired by invasive cancer cells suggest that this phenotype might be associated with lymph node metastasis and poor prognosis." (PMID 18722547, 2009).
pancreatic cancer (19 papers, 2012 to 2025). "The deficiency of TFF1 was associated with increased EMT of cancer cells in mouse models of pancreatic cancer, KPC." (PMID 38872370, 2024). "Considering these evidences, it seems plausible that TFF1 is closely associated with the stemness of neoplastic cells, and it is consistent with the finding of this study that TFF1 inhibits stemness of pancreatic cancer." (PMID 38872370, 2024). "AGR2, POSTN, TFF1, and CP were selected because their transcribed proteins have been previously implicated as potential biomarkers for pancreatic cancer." (PMID 36812168, 2023). "In addition, the rate of apoptotic cells was higher in the TFF1‐expressing cells than the control cells, confirming that the cellular expression of TFF1 is associated with the chemosensitivity of pancreatic cancer cells." (PMID 38872370, 2024). "We then hypothesized that the chemoresistance and EMT inhibited by TFF1 are closely associated with cancer stemness, and the stem cell markers of pancreatic cancer cell lines were investigated under gemcitabine and shTFF1 treatment." (PMID 38872370, 2024). "In their study, Patel & Mukherjee66 developed a neural network model using four urine biomarkers (REG1A, REG1B, LYVE1, and TFF1) to predict locally progressed pancreatic cancer." (PMID 40269234, 2025). "TFF1 has been documented to play a pivotal role in the progression of certain cancer types, including pancreatic cancer and gastric neoplasia, with its expression levels closely associated with tumor progression." (PMID 39539551, 2024). "In the context of primary pancreatic cancer, TFF1 was the marker for low ARS score, and REG4 is the marker for high ARS score." (PMID 40612666, 2024). "In terms of the cellular expression of TFF1, Panc1 cells show relatively high expression of TFF1 among various human pancreatic cancer cell lines." (PMID 38872370, 2024). "Given that deficiency of TFF1 in KC mice (the model with premalignant lesion) resulted in the development of pancreatic cancer, TFF1 functions to inhibit the initiation of malignant disease." (PMID 38872370, 2024). "To investigate the chemosensitivity of human pancreatic cancer, we assessed the expression of TFF1 in surgically resected human pancreatic cancer specimens." (PMID 38872370, 2024). "The aim of this study is to investigate the availability and functional mechanisms of trefoil factor family 1 (TFF1), a tumor‐suppressive protein in pancreatic carcinogenesis, to treat pancreatic cancer." (PMID 38872370, 2024). "MUC5AC/TFF1 co-expression was particularly common in mucinous carcinoma of the ovary, gastro-intestinal, and bilio-pancreatic neoplasms but also occurred in other entities." (PMID 39410561, 2024). "A study published in the journal PLOS ONE in 2017 found that TFF1 levels were significantly higher in the serum of pancreatic cancer patients compared to healthy controls and patients with pancreatitis." (PMID 37322046, 2023). "Another study published in the journal Oncotarget in 2018 found that TFF1 levels were higher in the urine of pancreatic cancer patients compared to healthy controls and patients with chronic pancreatitis." (PMID 37322046, 2023). "Lymphatic vascular endothelial hyaluronan receptor-1 (LYVE-1), regenerative gene-1-alpha (REG-1-alpha), and trefoil factor-1 (TFF-1) are potential biomarkers for the detection of early-stage pancreatic cancer isolated from urine." (PMID 35645371, 2022). "TFF1 is a member of the trefoil family and was reported to stimulated both pancreatic cancer and stellate cells and increases metastasis." (PMID 34055623, 2021). "In addition, overexpression of TFF1 inhibited Wnt signaling pathway in hepatocytes and pancreatic cancer cells in vitro." (PMID 40940735, 2025). "We transfected the TFF1 overexpression vector into the pancreatic cancer cell line Panc1." (PMID 38872370, 2024). "Combined therapy with TFF1 and traditional chemotherapy could be useful in pancreatic cancer treatment." (PMID 38872370, 2024).
pancreatic cancer (continued). "The chemosensitivity of the tumor was increased by injected TFF1; thus, combined therapy with TFF1 and traditional chemotherapy could be useful in pancreatic cancer treatment." (PMID 38872370, 2024). "This study clearly showed the efficacy of TFF1, if treated with gemcitabine, in inhibiting the tumor growth of pancreatic cancer in a xenograft model, suggesting that TFF1 might be useful to develop novel treatment for pancreatic cancer." (PMID 38872370, 2024). "Interestingly, the EMT phenotype may develop in pancreatic cancer cells with reduced TFF1 expression." (PMID 39682235, 2024). "Importantly, extracellularly administered TFF1 exhibit a similar function as cellular expression of TFF1, indicating that TFF1 therapy might be a promising approach for pancreatic cancer treatment in the near future." (PMID 38872370, 2024). "The illustration also indicates that age, sex, plasma CA19-9, creatinine, LYVE1, REG1B, TFF1, and REG1A have a positive correlation in the diagnosis of pancreatic cancer meaning that they are statistically significant predictors of pancreatic cancer diagnosis." (PMID 40269234, 2025). "In this study, we revealed that TFF1 acts as a tumor suppressor to inhibit EMT and cancer stemness, thus enhancing the chemosensitivity of pancreatic cancer." (PMID 38872370, 2024). "Here, we show that TFF1 can inhibit EMT and stemness, thus enhancing the chemosensitivity of pancreatic cancer." (PMID 38872370, 2024). "To further investigate the impact of gemcitabine/TFF1 treatment in vivo, we administered this treatment to a KPC mouse model of pancreatic cancer." (PMID 38872370, 2024). "Extracellular administration of TFF1 inhibited gemcitabine‐induced EMT, Wnt pathway activation and cancer stemness, eventually increased apoptosis of pancreatic cancer cells in vitro." (PMID 38872370, 2024). "TFF1 inhibits EMT and stemness in pancreatic cancer and the chemosensitivity of the tumor can be increased by injected TFF1." (PMID 38872370, 2024). "In another study, a neural network algorithm was employed to screen 140 datasets of individuals diagnosed with pancreatic cancer, for gene biomarkers in urine samples, namely REG1A/1B, LYVE1, TFF1, and CA19-9." (PMID 36358800, 2022). "In conclusion, we found that TFF1 inhibits EMT and stemness in pancreatic cancer." (PMID 38872370, 2024). "An overview of the TMA scores shows that TFF1, LAMC2 and AHNAK2 can be detected in pancreatic cancer samples with a score > 0 in 92, 93, and 53% of all samples, respectively, whereas at least one of the markers was detectable with a score > 0 in 99% of the samples." (PMID 29675033, 2018). "MRNA levels of AGR2, TFF1, and FXYD3 were greatly increased in pancreatic cancer cells when compared with non-cancerous cells." (PMID 39682235, 2024).
breast tumors (14 papers, 2007 to 2025). "The estrogen-responsive gene TFF1 is expressed in the majority of ERα+ breast tumors and exemplifies such heterogeneity, with transcriptional inactivity ranging from minutes to several days." (PMID 41000645, 2025). "In breast tumor tissue, TFF1 and TFF3 expression levels were inversely related to proliferation index (Ki67) and tumor grade." (PMID 36818673, 2022). "TFF1 is a small cysteine‐rich secreted protein that is frequently expressed in breast tumors under the control of estrogen." (PMID 32543775, 2020). "Besides, the gene expression analysis from the TCGA database showed that HOIL-1 was positively correlated with ERα target gene expression including GREB1 and TFF1 in breast tumors (P <0.01, R = 0.17; P = 0.008, R = 0.08 respectively)." (PMID 34094957, 2021). "More importantly, the majority of the published clinical observations have shown that TFF1-positive primary breast tumors have a better outcome profile, consistent with our finding that the wild-type alleles of the SNPs were associated with a decreased risk of poor survival." (PMID 25298020, 2014). "TCGA database analysis of 1080 breast tumors showed that RNF2 expression was positively correlated with estrogen signaling target genes expression (PDZK1, TFF1 and ESR1)." (PMID 36271315, 2023). "Clusters of genes containing some of the most important known markers of breast tumour phenotype are shown in greater detail: ESR1, MKI67, ERBB2, and TFF1." (PMID 17555561, 2007).
adenoma (12 papers, 2007 to 2025). A neoplasm arising from the epithelium. "All TFF1-deficient mice develop adenomas in the gastric mucosa, and 30% of them eventually progress to invasive carcinomas." (PMID 39410561, 2024). "Tff1-deficient (Tff1KO) mice obligatorily develop adenomas in the gastric antral/pyloric mucosa, and about 30% progress to carcinomas." (PMID 35628183, 2022). "Tff1-deficient (Tff1KO) mice obligatorily develop antropyloric adenoma and about 30% progress to carcinomas." (PMID 31963721, 2020). "Tff1-deficient mice obligatorily develop antropyloric adenoma and about 30% progress to carcinomas, indicating that Tff1 is a tumor suppressor." (PMID 32260357, 2020). "PCR analysis of individual adenomas from TMX-treated Tff1-CreERT2;Rnpc3lox/lox;Gp130F/F mice, identified cells with either a Rnpc3lox/lox or Rnpc3lox/Δ genotype, but no cells with a Rnpc3Δ/Δ genotype, where Δ represents a deleted (null) allele (Fig. EV2I)." (PMID 40624356, 2025). "In the Tff1-CreERT2; BrafLSL-V600E/+ mice, at 8 months post-tamoxifen induction, large adenomas were detected in the antrum of 10/15 mice, with similar histopathologic features to those in the KrasLSL-G12D/+ mice." (PMID 40673273, 2025). "In the Tff1-CreERT2; KrasLSL-G12D/+ mice, at 9 months post-tamoxifen induction, large adenomas were detected in one-third of the mice." (PMID 40673273, 2025). "Animal experiments showed that TFF1 knockout mice develop marked hyperplasia and dysplasia of gastric cells, antral/pylorus-specific adenoma and, in 30% of cases, multifocal intraepithelial or intramucosal carcinoma." (PMID 34679875, 2021). "In human gastric tissues, the expression of TFF1 has been found decreased in IM and adenomas compared with adjacent normal mucosa, and completely lost in about 40% to 60% of the carcinomas." (PMID 34679875, 2021). "Inactivation of Tff1 in mice (Tff1KO) predominantly results in a gastric phenotype, where all Tff1KO animals develop antropyloric adenoma with ~30% progressing to carcinoma." (PMID 32260357, 2020). "Homozygous mutant mice of Tff1 (Tff1-/-) develop antropyloric adenoma, and even multifocal carcinomas, consistent with increased inflammatory scores." (PMID 27713138, 2017). "An elegant, and also quite simple, experimental set-up to test this hypothesis would by a trial to cure Tff1KO mice from developing adenoma and carcinoma by the oral application of a recombinant Lactococcislactis strain secreting TFF1." (PMID 35628183, 2022). "For example, it could be tested whether oral application of short synthetic peptides mimicking the C-terminal end of xP1/TFF1 prevents formation of adenoma and carcinogenesis in Tff1KO mice." (PMID 31801293, 2019). "Antral adenomas harvested from TMX-treated Tff1-CreERT2;Rnpc3lox/lox;Gp130F/F mice contained 50% less Rnpc3 mRNA than antral adenomas from TMX-treated Rnpc3lox/lox;Gp130F/F (no Cre-transgene) controls (Fig. EV2H)." (PMID 40624356, 2025). "We found that recombination of Rnpc3lox alleles produced a reduction in total adenoma burden, again with a more marked effect on the corpus region than the antrum, compared to TMX-treated mice not carrying the Tff1-CreERT2 BAC transgene (Fig. EV2F,G)." (PMID 40624356, 2025).
lung adenocarcinoma (10 papers, 2016 to 2025). A carcinoma that arises from the lung and is characterized by the presence of malignant glandular epithelial cells. "In lung adenocarcinoma, elevated expression of TFF1 was repeatedly associated with resistance to Gefitinib and correlated with poor patient prognosis, indicating its potential as a therapeutic target." (PMID 41020875, 2025). "In lung adenocarcinoma, TFF1 gene expression is significantly associated with larger tumor size and acinar subtype." (PMID 27081700, 2016). "TFF-1 is highly expressed in lung adenocarcinoma, while Napsin A exhibits high specificity and sensitivity in lung adenocarcinoma." (PMID 38914812, 2024). "This is recently shown for MUC21 overexpression as influencing the development of lung adenocarcinoma and TFF1 influencing epithelial-mesenchymal transition." (PMID 33308144, 2020).